TYMP (thymidine phosphorylase)
Diseases named in the same sentence as TYMP in open-access papers (continued):
Sharing a sentence is not in itself a finding about the gene and the disease.
rectal cancer (5 papers, 2006 to 2025). A primary or metastatic malignant neoplasm that affects the rectum. "The expression of TYMP is closely associated with rectal cancer treatment outcomes." (PMID 40303404, 2025). "Preoperative radiotherapy or chemoradiotherapy (CRT) is considered the standard treatment for locally advanced rectal cancer, and studies have shown that TYMP expression can help predict the efficacy of CRT." (PMID 40303404, 2025). "For example, when the expression levels of several 5-FU-related genes in micro- and macrodissected tumor tissues of patients with locally advanced rectal cancer who subsequently received radiotherapy were compared, a significant difference in TYMP gene expression was found." (PMID 35567733, 2022). "Studies about thymidine phosphorylase and thymidylate synthase concluded that the expression of these markers could be associated with response to just chemotherapy in rectal cancers, with no considerations about survival differences." (PMID 28326100, 2017). "Additionally, the combined expression of TYMP and hypoxia-inducible factor α (HIF-1α) has been shown to predict the prognosis of patients with rectal cancer undergoing neoadjuvant chemoradiotherapy with oxaliplatin and capecitabine (XELOXART)." (PMID 40303404, 2025). "Tumour expression of thymidylate synthase, thymidine phosphorylase, cyclin A, vascular endothelial growth factor (VEGF), carbonic anhydrase-9, hypoxia inducible factor-1α, and glucose transporter-1 (GLUT-1) proteins was determined before and after rectal cancer surgery." (PMID 17016487, 2006).
hepatocellular carcinoma (4 papers, 2014 to 2024). A malignant tumor that arises from hepatocytes. "It has been reported that increased TYMP expression in human hepatocellular carcinoma correlates with a high incidence of portal vein tumor thrombosis." (PMID 33829029, 2021).
Leukoencephalopathy (4 papers, 2018 to 2021). This term describes abnormality of the white matter of the cerebrum resulting from damage to the myelin sheaths of nerve cells. "Such mutations generate a severe thymidine phosphorylase deficiency leading to ptosis, progressive ophthalmoplegia, gastrointestinal dysmotility, cachexia, peripheral neuropathy, and leukoencephalopathy." (PMID 32887417, 2020). "Thus, thymidine phosphorylase deficiency should be suspected in cases where gastrointestinal and neurological involvement coexist, particularly where there is leukoencephalopathy on MRI or abnormalities of ocular motility." (PMID 30627136, 2018). "If leukoencephalopathy is then detected, the algorithm suggests biochemical testing for metabolite excess in biofluids, followed by the sequencing of the TYMP gene, should an accumulation of thymidine and deoxyuridine be identified." (PMID 30627136, 2018). "Therefore, the leukoencephalopathy in MNGIE may be a consequence of the absence of the inhibitory activity of thymidine phosphorylase, rather than its catalytic activity." (PMID 30959750, 2019).
pancreatic cancer (4 papers, 2017 to 2024). "Expression of these genes, which are involved in 5-FU conversion to FdUMP, also correlated with expression of the FdUMP efflux transporter ABCC5 (TK1 and ABCC5 r = 0.78, p = 0.001 and TYMP and ABCC5 r = 0.86, p < 0.0001) in pancreatic tumour." (PMID 34132895, 2021). "The positive correlation between TYMP and TK1 expression in pancreatic tumours supports this possibility." (PMID 34132895, 2021). "Even though gemcitabine is delivered into the cancer cells, gemcitabine is quickly metabolized to non-toxic metabolites like cytosine by thymidine phosphorylase and other enzymes, which would reduce the antiproliferative activity in pancreatic cancer cells." (PMID 28796151, 2017).
prostate carcinoma (4 papers, 2002 to 2015). A carcinoma that arises from epithelial cells of the prostate gland. "Thymidine phosphorylase is an important angiogenic stimulus in prostate carcinomas and, as would be expected, it is associated with high MVD." (PMID 11986782, 2002). "High thymidine phosphorylase cancer cells and thymidine phosphorylase stromal cells expression was associated with high angiogenesis in prostate carcinomas, and this significant association was extended to include both tumour-associated macrophages and tumour-infiltrating lymphocytes." (PMID 11986782, 2002). "TYMP is overexpressed in various tumors including prostate cancer and plays an important role in angiogenesis, tumor growth invasion, and metastasis." (PMID 25215235, 2014). "In conclusion, thymidine phosphorylase is a major angiogenic factor in prostate carcinomas and its up-regulation is likely to occur in the context of a host immune response." (PMID 11986782, 2002). "Moreover immunohistochemical analysis of prostate carcinoma tissue suggests high levels of thymidine phosphorylase in certain types of prostate." (PMID 18794792, 2008).
glioblastoma (3 papers, 2013 to 2023). The most malignant astrocytic tumor (WHO grade IV). "Glioblastomas have a greatly upregulated thymidine phosphorylase content and activity." (PMID 35626167, 2022). "hnRNP H drives an oncogenic switch in glioblastoma multiforme (GBM) cells by promoting of aberrant splicing of MADD and RON, whereas H1/H2-mediated unsplicing of thymidine phosphorylase results in antitumor drug resistance in leukemia cells." (PMID 36830718, 2023). "Experimental (non-marketed) thymidine phosphorylase inhibitors have no cytotoxicity alone, but are synergistic with temozolomide against glioblastoma cell lines." (PMID 35626167, 2022).
myeloma (3 papers, 2021 to 2025). "TYMP overexpression is commonly observed in bone metastatic tumors, further supporting the potential of TYMP-targeted therapies for treating myeloma-related bone diseases." (PMID 40303404, 2025). "In turn, myeloma cell–secreted 2-deoxy-D-ribose, the product of thymidine catalyzed by the function of thymidine phosphorylase, upregulates CIITA expression in osteocytes through the STAT1/IRF1 signaling pathway." (PMID 35760800, 2022).
psoriasis (3 papers, 2020 to 2024). An autoimmune condition characterized by red, well-delineated plaques with silvery scales that are usually on the extensor surfaces and scalp. "The PPI results and friends analysis demonstrated strong correlations between S100A9, S100A8, NAMPT, TYMP and others, suggesting their potential involvement in the regulation of PANoptosis in psoriasis." (PMID 39480805, 2024). "A few DEPs, such as SERPINC1, SERPINF2, F2, PLXDC2, and TYMP, were also involved in regulating blood coagulation and angiogenesis, which plays an essential role in the pathogenesis and maintenance of psoriasis." (PMID 36483564, 2022). "In a study evaluating the treatment of psoriasis with IL-17A and TNF-α inhibitors, it was observed that the differential expression of the protein TYMP before and after treatment was significant." (PMID 39480805, 2024). "PRM validation of 9 proteins that were highly expressed in the drug metabolism pathway further confirmed significant upregulation of MPO (17.05), TYMP (2.44), and IMPDH2 (1.78) in psoriasis lesions." (PMID 32817748, 2020). "The proteins identified in our previous study, including MPO, TYMP, IMPDH, ALDHs, and GSTT1, were also highly expressed in this study, which indicated that drug metabolism played an important role in the pathogenesis of psoriasis." (PMID 32817748, 2020).
Stroke (3 papers, 2021 to 2022). Sudden impairment of blood flow to a part of the brain due to occlusion or rupture of an artery to the brain. "The differences in the concentrations of interferon regulatory factor 7 (IRF7) and thymidine phosphorylase TYMP-4 persisted for the next three days from the onset of stroke (a significant difference between group B and the control)." (PMID 35268287, 2022). "Therefore, it is important to consider the effect of TYMP inhibiting on outcome in humans after stroke." (PMID 35054033, 2022). "In fact, TYMP released from macrophages contributes to the formation of atherosclerotic plaques, thus leading to fatal cardiovascular disorders, including myocardial infarction and stroke." (PMID 34589604, 2021).
cholangiocarcinoma (2 papers, 2014 to 2022). A carcinoma that arises from the intrahepatic biliary tree (intrahepatic cholangiocarcinoma) or from the junction, or adjacent to the junction, of the right and left hepatic ducts (hilar cholangiocarcinoma). "Pyrimethamine in cholangiocarcinoma: In cholangiocarcinoma, upregulated thymidine phosphorylase also contributes to chemotherapy resistance, and furthers survival." (PMID 35626167, 2022). "Thymidine phosphorylase overexpression enhances growth and suppresses apoptosis in human umbilical vein endothelial cells, as well as increasing VEGF, IL-8, and the growth of cholangiocarcinoma cells." (PMID 35626167, 2022).
Cirrhosis (2 papers, 2020 to 2022). A chronic disorder of the liver in which liver tissue becomes scarred and is partially replaced by regenerative nodules and fibrotic tissue resulting in loss of liver function. "Seven DEGs (TYMP, TYROBP, CD14, TGFBI, LILRA2, GNLY, and GZMB) were common to HCC, cirrhosis, and CHB when compared to healthy controls." (PMID 35265561, 2022).
diabetes (2 papers, 2021 to 2022). "The implication of TP variants in atypical forms of monogenic diabetes shows that genetic diagnosis of lipodystrophic syndromes should include TYMP analysis." (PMID 35341481, 2022).
endometriosis (2 papers, 2022 to 2025). The growth of functional endometrial tissue in anatomic sites outside the uterine body. "SSTR5, KCNH2, CASP3, PTGER1, PPARD, and TYMP emerged as the top-ranked targets, indicating their potential significance in the treatment of endometriosis." (PMID 39754173, 2025). "Among the 15 DEPs, COL1A1, COL6A2, and NID2 are among the proteins with strong interactions, and MT2A, TYMP, COL1A1, and COL6A2 have already been associated with endometriosis." (PMID 36232817, 2022).
endothelial dysfunction (2 papers, 2023 to 2024). In vascular diseases, endothelial dysfunction is a systemic pathological state of the endothelium (the inner lining of blood vessels) and can be broadly defined as an imbalance between vasodilating and vasoconstricting substances produced by (or acting on) the endothelium. "Specifically, TYMP, which promotes angiogenesis and stimulates the growth of endothelial cells, was already found associated with endothelial dysfunction and induced diabetic-like symptoms in studies of type 2 diabetes, but has not been described in the context of schizophrenia." (PMID 38573526, 2024). "Therefore, pharmacological inhibition of TYMP might mitigate endothelial dysfunction." (PMID 37100811, 2023).
follicular adenoma (2 papers, 2024 to 2025). "Regarding the relationship between TYMP and thyroid disease, a previous study suggested that TYMP is a candidate biomarker for thyroid follicular adenomas." (PMID 39807704, 2025). "Comparative proteomics analysis using a high-performance liquid chromatography-tandem mass spectrometry approach revealed TSPAN30, DDB1, TYMP, VDAC2, and DCXR as the top five candidate biomarkers for directly comparing samples of follicular adenoma and normal thyroid tissue." (PMID 38649381, 2024).
glioma (2 papers, 2013 to 2022). A benign or malignant brain and spinal cord tumor that arises from glial cells (astrocytes, oligodendrocytes, ependymal cells). "The volcano plot revealed that glial cells in C5 derived from TDL upregulated expression of myelin-related genes (TYMP, CD9, MAG, and PMP22) and immune-related and inflammatory response-associated genes (IL1B and CXCL8) comparing to those from glioma." (PMID 36085357, 2022).
invasive breast carcinoma (2 papers, 1998 to 2020). A carcinoma that infiltrates the breast parenchyma. "The gene expressions of ACOT7, STAT1, TYMP, and VOPP1 were significantly increased in invasive breast carcinoma, while the gene expressions of ACTG2, CNN1, CDC14B, NFIB, RCN1, and TRIM2 were dramatically downregulated in BRCA." (PMID 31986487, 2020).
ischemic stroke (2 papers, 2022). A stroke disorder caused by obstruction of blood flow to the brain, due to thrombotic (local blood clot formation) or embolic (due to a blood clot or other material traveling from another site) event. "Differences were observed in the serum proteome of people with ischemic stroke compared to the control group, identifying two proteins: TYMP and β-Ala His dipeptidase." (PMID 35054033, 2022). "In the present study, the increase in TYMP levels was observed in the acute phase of ischemic stroke." (PMID 35054033, 2022). "Interestingly, we have shown dynamic changes in the expression of the thymidine phosphorylase TYMP-4 during ischemic stroke, which was significantly higher as compared with the controls." (PMID 35268287, 2022). "The activity of TYMP facilitating the formation of blood clots, disrupting homeostasis, and breaking the blood-brain barrier suggests that inhibition of this enzyme activity may lead to prevention of ischemic stroke." (PMID 35054033, 2022).
lung adenocarcinoma (2 papers, 2020 to 2021). A carcinoma that arises from the lung and is characterized by the presence of malignant glandular epithelial cells. "In a summary, CDA and TYMP expression positively correlate with the EMT status in lung adenocarcinoma patient samples." (PMID 33874986, 2021). "In summary, chemotherapy treatment generally increased CDA and TYMP expression and activity in lung adenocarcinoma cell lines." (PMID 33874986, 2021). "We took advantage of the publically available TCGA database containing 517 cases of primary lung adenocarcinoma tumors and performed an in-silico mRNA expression analysis of CDA, TYMP and several EMT markers." (PMID 33874986, 2021). "Further analysis based on the overall survival of 502 lung adenocarcinoma patients, revealed that low expression of CDA correlated with a better survival, while TYMP expression levels did not correlate with survival." (PMID 33874986, 2021).
melanoma (2 papers, 2013 to 2024). A malignant, usually aggressive tumor composed of atypical, neoplastic melanocytes. "The more interesting ones, confirmed by the bibliography on melanoma, are as follows: USP15, TIPIN, TMC5, TYMP, USP19, USP8, and TFAP2B." (PMID 38928466, 2024).
mucinous tumors (2 papers, 2021 to 2022). "The TYMP gene expression in mucinous tumors was higher than well/moderately but lower than poorly differentiated tumors, with the exception of stromaTYMP." (PMID 35567733, 2022). "One gene associated with 5-FU resistance, thymidine phosphorylase (TYMP), was found to have an SSM rate of 5.97% in mucinous tumors compared with only 1.08% in non-mucinous tumors." (PMID 33808549, 2021).
nasopharyngeal carcinoma (2 papers, 2009 to 2015). A carcinoma arising from the nasopharyngeal epithelium. "An important role has been suggested for cytoplasmic hnRNP K in nasopharyngeal carcinoma and metastasis, where aberrant cytoplasmic localisation of hnRNP K along with overexpression of thymidine phosphorylase is associated with shorter overall survival and lower metastasis-free survival." (PMID 19401687, 2009).
ovarian tumor (2 papers, 2011 to 2015). "For example, 4-MU was recently reported to inhibit growth of an ovarian tumor cell line via suppression of thymidine phosphorylase (TP) mRNA." (PMID 25852691, 2015).
renal cell carcinoma (2 papers, 2015 to 2025). "Recent studies have shown that a reduction in TYMP expression can significantly affect the proliferation, migration, and invasion of renal cell carcinoma (RCC) cells in vitro." (PMID 40303404, 2025).
thrombosis (2 papers, 2021 to 2022). "However, TYMP expression is high in several systemic diseases that are associated with a high risk of thrombosis." (PMID 33829029, 2021). "We also show here that pulmonary thrombosis enhances tumorigenesis in a manner that is dependent upon myeloid cell HIFs 1 and 2 and that thrombosis-induced tumorigenesis seems to be regulated by paracrine factors such as thymidine phosphorylase (TP)." (PMID 36291563, 2022).
triple-negative breast carcinoma (2 papers, 2021 to 2022). An invasive breast carcinoma which is negative for expression of estrogen receptor (ER), progesterone receptor (PR), and human epidermal growth factor receptor 2 (HER2). "In triple-negative breast cancer, increased TYMP expression was significantly related with a positive reaction to capecitabine." (PMID 36276080, 2022). "It was reported that TYMP overexpression correlates with TYMS KO sensitivity in cell lines and antifolate treatment in triple negative breast cancer patients." (PMID 34454516, 2021).
acute leukemia (1 paper, 2022). A clonal (malignant) hematopoietic disorder with an acute onset, affecting the bone marrow and the peripheral blood. "We also demonstrated that KMT2A-r acute leukemia patients overexpress three genes (ALDH3A1, PIK3R2, and TYMP) with interaction annotation to 5-Fluorouracil." (PMID 35734412, 2022).
bile duct cancer (1 paper, 2010). "Immunohistochemical analysis revealed that thymidine phosphorylase expression was significantly higher in gallbladder cancer than in bile duct cancer." (PMID 20955617, 2010). "In addition, we hypothesize that high expression of thymidine phosphorylase by gallbladder cancer results in a higher response rate to capecitabine by gallbladder cancer than bile duct cancer." (PMID 20955617, 2010).
biliary tract cancer (1 paper, 2010).
bladder tumours (1 paper, 2002). "For example, expression of the angiogenic factor thymidine phosphorylase (TP) is significantly higher in invasive than in superficial bladder tumours." (PMID 11953885, 2002).
breast tumour (1 paper, 2005). "In this study, we measured total and free VEGF, sVEGFR-1 and VEGFR-2, as well as Her-2/neu and thymidine phosphorylase (TP) levels in breast tumour cytosols quantitatively and then evaluated those prognostic values." (PMID 15668703, 2005).
cervical cancer (1 paper, 2025). A primary or metastatic malignant neoplasm involving the cervix. "The analysis showed that OAS2, KLHDC7B, STAT1, TYMP, PSME2 and GBP5 were significantly upregulated in cervical cancer cells compared with normal epithelial cells." (PMID 40259929, 2025).
cholesteatoma (1 paper, 2015). A pathologic process characterized by the proliferation of keratinizing squamous epithelium resulting in the accumulation of keratin and cells in the middle ear and/or mastoid. "TYMP abundance was elevated in cholesteatoma 3.25-fold in our study compared to mucosa, though less so compared to post-auricular skin." (PMID 26608071, 2015).
chronic lymphocytic leukemia (1 paper, 2025). "The TYMP gene exhibited strong associations with several conditions, including other enteritis, intestinal obstruction, shoulder joint disorders, chronic lymphocytic leukemia, non-infectious enteritis, and intestinal stenosis." (PMID 41142241, 2025).
Erythema (1 paper, 2016). Redness of the skin, caused by hyperemia of the capillaries in the lower layers of the skin. "Upregulation of thymidine phosphorylase by previous external radiotherapy gave rise to development of angiogenesis in the previously irradiated region, leading to hypervascularity and erythema." (PMID 27604462, 2016).